PPARD (peroxisome proliferator activated receptor delta)
Diseases named in the same sentence as PPARD in open-access papers (continued):
Sharing a sentence is not in itself a finding about the gene and the disease.
heart failure (18 papers, 2010 to 2025). Inability of the heart to pump blood at an adequate rate to meet tissue metabolic requirements. "Inborn cardiomyocyte-restricted PPARδ deletion leads to cardiomyopathy and heart failure with impaired myocardial FAO." (PMID 31032335, 2018). "For example, myocardial hypoxia induces expression of the miR-199a:214 cluster which thereafter downregulates several cardiac and mitochondrial targets, such as PPARδ, downregulation of PPARδ provokes glycolytic metabolism in heart failure." (PMID 29109913, 2017). "Previous studies have shown that induces expression of miR-214 that actively downregulate several mitochondrial and cardiac targets including PPARδ, provoking a switch toward a glycolytic metabolic profile that contributes to heart failure." (PMID 26572862, 2015). "The present study investigated the merit of ginseng in the improvement of heart failure in diabetic rats and the role of peroxisome proliferator-activated receptors δ (PPARδ)." (PMID 24745017, 2014). "Deletion of cardiac PPARδ is mentioned to result in decreased contraction and lowered cardiac output, showing an incidence of cardiac failure." (PMID 24745017, 2014). "This is consistent with the view that cardiac PPARδ is mediated in contraction of heart and decrease of PPARδ is related to higher incidence of cardiac failure." (PMID 23533379, 2013). "The deletion of cardiac PPARδ results in decreased contraction, increased left ventricular end-diastolic pressure, lowered cardiac output, and increased incidences of cardiac failure." (PMID 22666095, 2012). "Because dobutamine is an agent widely used to treat heart failure in emergency setting, this study is aimed to investigate the change of PPARδ in response to dobutamine." (PMID 22666095, 2012). "In addition to depressed FAO, cardiomyocyte-restricted PPARδ knockout mice develop severe phenotypic changes, such as cardiac dysfunction, myocardial lipid accumulation and progressive heart failure." (PMID 31032335, 2018). "Cardiac PPARδ deletion induces cardiac dysfunction, hypertrophy, and heart failure in rodents." (PMID 28672855, 2017). "On the other hand, PPARD is a critical regulator of fatty acid oxidation in cardiac tissue and its lack of expression has been associated with the onset of cardiac failure." (PMID 23372767, 2013). "Thus, in the present study, we used Wistar rats and primary neonatal rat cardiomyocytes to investigate the role of PPARδ in DOX-induced heart failure both in vivo and in vitro." (PMID 23533379, 2013). "Deletion of cardiac PPARδ, which is accompanied by decreased contraction, increased left ventricular end-diastolic pressure, and lowered cardiac output, leads to decreased contraction and increased incidence of cardiac failure." (PMID 23533379, 2013). "Deletion of cardiac PPARδ, is accompanied by decreased contraction, increased left ventricular end-diastolic pressure and lowered cardiac output, and leads to decreased contraction and increased incidence of cardiac failure." (PMID 23724037, 2013). "Thus, we suggest that ginseng could improve heart failure through the increased PPARδ expression in STZ-rats." (PMID 24745017, 2014). "Thus, to the best of our knowledge, this is the first study to show that ginseng could restore heart failure through an activation of PPARδ in type 1-like diabetic rats." (PMID 24745017, 2014). "Inborn cardiomyocyte-restricted PPARδ deletion impairs myocardial FAO and leads to cardiomyopathy and heart failure." (PMID 31032335, 2018). "Thus, PPARδ may be a suitable target for the development of inotropic agents to treat heart failure without changing heart rate." (PMID 23724037, 2013). "In diabetic rats with heart failure, GW0742 at a dose sufficient to activate PPARδ reversed cardiac contraction without changes in heart rate." (PMID 23724037, 2013).
Alzheimer disease (17 papers, 2011 to 2024). A progressive, neurodegenerative disease characterized by loss of function and death of nerve cells in several areas of the brain leading to loss of cognitive function such as memory and language. "However, evidence suggests that targeting PPARγ and/or PPARδ can improve memory deficits and/or the pathology associated with Alzheimer’s disease in rodent models." (PMID 37190025, 2023). "Agonists of PPARδ affect energy homeostasis, anti-inflammation and insulin sensitivity and present an attractive target in Alzheimer’s disease pathogenesis." (PMID 34428743, 2021). "The activation of PPARδ induced by a neurotransmitter involved in neurological disorders such as Alzheimer’s disease and reduced the intracellular ROS accumulation." (PMID 28962559, 2017). "Although data regarding PPARδ are limited, studies have demonstrated that administration of PPARδ agonists confers neuroprotection following various acute and chronic injuries to the CNS, such as stroke, multiple sclerosis, and Alzheimer's disease." (PMID 22135673, 2011). "To date, the neuroprotective benefits of PPARδ agonists have been observed in models of stroke, multiple sclerosis, Alzheimer's disease, Parkinson's disease, radiation-induced brain injury, and spinal cord injury." (PMID 22135673, 2011). "Variants of the rs8192678 PGC-1α polymorphism have previously been studied alongside polymorphisms in peroxisome proliferator-activated receptor delta (PPARD) and sirtuin 1 (SIRT1) in relation to Alzheimer's disease and were found not to be associated with AD in a Finnish case-control situation." (PMID 21595954, 2011).
steatosis (16 papers, 2010 to 2024). Increased lipid within the cytoplasm of cells. "Studies have also reported that the PPAR pan-agonist can reduce steatosis, reverse liver injury and monocyte infiltration, and reduce the inflammatory response in macrophages and monocytes with the participation of PPARδ." (PMID 35178098, 2022). "In a similar way, myeloid-specific PPARδ−/− mice fed a high-fat diet gain more weight, acquire a higher body weight/liver weight ratio, and have a more profound steatosis than control animals." (PMID 20508742, 2010). "PPARδ is thus an interesting potential pharmacological target for the induction of M2 activation to control inflammation and improve steatosis in NAFLD." (PMID 20508742, 2010). "However, there is concurrent increase in PPARα and PPARδ levels which would be expected to result in enhanced oxidation of lipids and resolution of steatosis." (PMID 23483972, 2013). "Genes involved in steatosis (Cd36, Lpl), hepatoxicity (Avpr1a, Pla2g12a), necrosis (Serpine1), fatty acid metabolism (Acox1, Cpt1b, Cyp4a10, Ehhadh), lipid transport (Apoa1), and PPAR transcription factors (Pparδ) were altered with PFHpS exposure compared to vehicle-exposed animals." (PMID 39066581, 2024).
myocardial infarction (14 papers, 2014 to 2025). Gross necrosis of the myocardium, as a result of interruption of the blood supply to the area, as in coronary thrombosis. "An early study on rats shows the PPARδ agonist GW0742 protects against right heart hypertrophy from post-myocardial infarction." (PMID 31032335, 2018). "Activating PPARδ signaling after myocardial infarction (MI) induces cardiomyocyte cell cycle activity and improves scarring as well as cardiac function." (PMID 31032335, 2018). "Notably, inducible cardiomyocyte-specific overexpression of constitutively active PPARδ as well as treatment with PPARδ agonist after myocardial infarction in mice induced cell cycle progression in cardiomyocytes, reduced scarring, and improved cardiac function." (PMID 28621328, 2017). "Here we show that carbacyclin induces cardiomyocyte proliferation via a PPARδ/PDK1/p308Akt/GSK3β/β-catenin-pathway and that activated PPARδ signaling after myocardial infarction (MI) induces cardiomyocyte cell cycle activity and improves scarring as well as cardiac function." (PMID 28621328, 2017). "To determine whether PPARδ activation is sufficient to improve the ineffective myocardial repair that takes place after myocardial infarction (MI) in mice, we induced MI by ligation of the left anterior descending artery (LAD) in adult TMCM (control) and TMVPD (caPPARδ) mice." (PMID 28621328, 2017).
ovarian carcinoma (14 papers, 2008 to 2023). A malignant neoplasm originating from the surface ovarian epithelium. "PPARδ promotes lipid accumulation in macrophages, and this may explain the high concentration of PUFAs and constant upregulation of PPARβ/δ in tumour-associated macrophages (TAMs) in ovarian cancer ascites, which play a pro-tumorigenic role in tumour microenvironment." (PMID 31334678, 2019). "Aspirin, a COX-1 selective inhibitor, inhibits growth of ovarian cancer and attenuates PPARδ function, implicating PPARδ inactivation in growth inhibition of ovarian cancer." (PMID 25734181, 2015). "Therefore, much more efforts are demanded to reveal the mechanism of DOCK4 targeted by PPARδ in ovarian cancer patients' immune cells, especially neutrophils." (PMID 33613670, 2021). "However, another study showed that aspirin did not inhibit ovarian cancer growth and further studies are required to examine the role of PPARδ in malignant tumors." (PMID 25734181, 2015).
pancreatic cancer (14 papers, 2013 to 2025). "In particular, activation of PPARδ negatively regulates invasion and metastasis of human pancreatic cancer cells by downregulating genes associated with these biological processes, thereby supporting the findings presented herein." (PMID 29212212, 2017). "The authors further found that GOT2 was localized in the nucleus in pancreatic cancer cells and acted as a fatty acid-binding protein to regulate the transport of nuclear fatty acids, and bind to and activate PPARδ, promoting its transcriptional activity." (PMID 40247913, 2025). "A landmark study confirmed that PPARδ undermines anti-tumor immunity and promotes immune evasion in murine models of pancreatic cancer." (PMID 37833991, 2023). "PPARδ upregulation in human pancreatic cancers correlates with higher pathological stages and a higher risk of metastasis." (PMID 35562376, 2022). "Nutrient starvation and microenvironmental signals activate PPARδ in pancreatic cancer to support survival and metastasis by promoting metabolic plasticity and invasiveness, providing a strong rationale for developing PPARδ-targeted therapies for pancreatic cancer." (PMID 40607925, 2025). "This CCL2/CCR2 axis drives an immunosuppressive tissue microenvironment, which may be targeted by PPARδ antagonists to prevent lethal pancreatic cancer." (PMID 37833991, 2023). "We found that PPARδ in Panc02 mouse PDAC cells strongly promoted pancreatic cancer metastasis." (PMID 35562376, 2022). "Moreover, nuclear GOT2 has been shown to promote the transport of fatty acids, such as arachidonic acid, by interacting with peroxisome proliferator-activated receptor δ (PPARδ) and markedly activating the PPARδ signaling pathway in a mouse pancreatic cancer cell line." (PMID 41451371, 2025). "PPARδ and MEK/ERK1/2 signaling pathways affect differentially the expression of Δ6D in pancreatic cancer cells." (PMID 24294133, 2013). "The aim of the present study was to investigate the effect of peroxisome proliferative-activated receptor δ (PPARδ) agonist and MEK/ERK1/2-dependent pathway on the expression of Δ6D in human pancreatic carcinoma cell line PANC-1." (PMID 24294133, 2013). "Our study showed that PPARδ and ERK1/2 MAPK signaling pathways affect the gene expression of Δ6D in pancreatic carcinoma cell line PANC-1." (PMID 24294133, 2013). "In the present study in human pancreatic carcinoma cell line PANC-1, Δ6D expression was tested for responsiveness to the synthetic PPARδ agonist GW0742, under either MEK/ERK1/2 or epidermal growth factor receptor (EGFR) signaling pathway blockade." (PMID 24294133, 2013). "Specifically, PPARδ reduced mitochondrial oxygen consumption and boosted the glycolytic capacity by altering the ratio of MYC and PGC1A expression, two key regulators of pancreatic cancer metabolism." (PMID 40607925, 2025). "In this study, it was demonstrated that PPARδ agonist GW0742 could markedly increase Δ6D gene and protein expression in pancreatic carcinoma cell line PANC-1." (PMID 24294133, 2013).
colitis (13 papers, 2008 to 2025). Inflammation of the colon. "Ligands for PPARδ, including n-3-PUFAs, are anti-inflammatory, and at high concentrations PPARδ activation attenuates experimental colitis and intestinal inflammation, whereas PPARδ null mice have increased sensitivity to DSS-colitis." (PMID 33603741, 2020). "In colon tumorigenesis and colitis, Ptgs2 and prostaglandin synthesis are dependent on PPARδ, whereas inhibition of tumorigenesis by NSAIDs results from induction of the endogenous PPARδ antagonist, 13-S-hydroxyoctadecadienoic acid." (PMID 28077942, 2016). "However, another study demonstrated that PPARδ upregulates COX-2 in mouse gut epithelial cells, leading to an increase in macrophage-produced proinflammatory cytokines and increased the risk of colonic inflammation." (PMID 35003101, 2021). "One study showed that dual activation of PPARδ and PPARγ using conjugated linoleic acid (CLA) downregulated both TNFα and NFκβ activation while upregulating TGF-β1 as well as protecting against DSS and CD4 induced colitis in mice." (PMID 35003101, 2021).
neuroblastoma (13 papers, 2008 to 2025). Neuroblastoma (NB) is the most common solid, extracranial childhood tumor. "Somatic PPARD variants were described also in lung, breast, ovary, endometria, liver, and prostate tumor, and neuroblastoma." (PMID 24391853, 2013). "We identified that PPARδ inhibited 6-hydroxydopamine (6-OHDA)-triggered neurotoxicity in SH-SY5Y neuroblastoma cells." (PMID 35624674, 2022). "PPARD identified following DAT of MPN was found to be interacting with FABP5 (found in DAT of neuroblastoma cells)." (PMID 34394070, 2021). "Low PPARδ and ALOX5 expression was associated with MYCN amplification in a cohort of 251 primary neuroblastoma tumours." (PMID 23874790, 2013). "In this study we found that ATRA or 5-oxo-ETE treatment activated PPARδ-mediated PPRE-reporter activity in neuroblastoma cells." (PMID 23874790, 2013). "Celecoxib also promotes death of neuroblastoma cells synergistically in combination with cytotoxic drugs in vitro and in vivo, therefore it is important to determine if PPARδ signalling is a common mechanism of drug resistance in cancer." (PMID 23874790, 2013). "The effects of the PPARδ agonist GW0742 and the antagonist GSK0660 on MPP+-induced cytotoxicity in SH-SY5Y cells, a dopaminergic neuroblastoma cell line, were investigated." (PMID 23500098, 2013).
skin cancer (13 papers, 2008 to 2023). "Consistent with this, overexpression of PPARδ causes AOM-induced colon tumorigenesis, and ultraviolet (UV)-induced PPARδ expression leads to Src activation and EGFR/ERK signaling-mediated skin cancer in mice." (PMID 28948004, 2017).
gastric cancer (11 papers, 2010 to 2023). A primary or metastatic malignant neoplasm involving the stomach. "One of the studies developed gastric cancer tumors spontaneously by overexpressing peroxisome proliferator-activated receptor delta (PPARD) in villin-positive gastric progenitor cells." (PMID 37233647, 2023). "In gastric cancer, researchers found that overexpression of PPARδ in the villin promoter of mice quiescent gastric progenitor cells promoted the occurrence of spontaneously invasive gastric adenocarcinomas." (PMID 35151320, 2022). "While cyclin D1 and CDK4 are well known biomarker of cell proliferation, uPAR and PPARδ have been reported to play role in the migration and invasion of gastric cancer cells." (PMID 22710759, 2012). "The present study describes a new model of metastatic gastric cancer that is dependent on the tumor promoting activity of PPARδ agonist GW510516 following carcinogen administration." (PMID 21318167, 2010). "PPARδ has been found to be differentially expressed in several major human cancers including colorectal cancer, gastric cancer and prostate cancer, and may function as oncogene or tumor suppressor through diverse mechanisms." (PMID 35151320, 2022). "PPARδ collaborates with the hippo coactivator YAP1 to elevate the expression level of SOX9 and the progression of gastric cancer." (PMID 37183261, 2023). "In summary, we describe a rapidly developing metastatic gastric cancer model dependent on the tumor-promoting effects of GW501516 following carcinogen treatment, which suggests a proinflammatory switch in PPARδ function." (PMID 21318167, 2010).
liver fibrosis (11 papers, 2007 to 2025). "The effect of PPARD agonists on liver fibrosis is a robust finding in mice; however, the evidence for the reduction of liver fibrosis in humans remains unestablished." (PMID 41180305, 2025). "PPARD agonist GW501516 attenuated hepatic fibrosis by reducing SMAD3 phosphorylation and p300 levels via AMP-activated protein kinase in HSCs, using mice and LX-2 cell lines." (PMID 39899669, 2025). "Rats with carbon tetrachloride-induced liver fibrosis had oxidative stress and increased PPARδ gene expression." (PMID 25993297, 2015). "Furthermore, some studies have found that the activation of PPARδ can induce the anti-inflammatory effects of macrophages, reduce liver inflammation, and improve liver fibrosis." (PMID 39108746, 2024). "The PPARD agonist KD3010 showed strong antifibrotic effects in mouse models of liver fibrosis, although it did not exert a direct effect on HSCs." (PMID 39899669, 2025). "Accordingly, these compounds of HQD may prevent the further development of liver fibrosis by alleviating liver inflammation through influencing the expression of PTGS2, PPARD, and PPARG." (PMID 34301291, 2021).
adenoma (10 papers, 2006 to 2024). A neoplasm arising from the epithelium. "However, other studies have shown that activation of another member of the PPAR family, PPARδ, enhances the stemness and function of ISCs while also increasing the risk of adenoma." (PMID 38575595, 2024). "Inactivation of PPARδ has been shown to reduce colon inflammation and adenoma formation, which highlights the inflammatory role played by PPARδ." (PMID 38791211, 2024). "Deletion of PPARδ decreasedintestinal adenoma growth and inhibited the tumor-promoting effects of a PPARδagonist." (PMID 18528523, 2008). "A subsequentgenetic study showed that deletion of PPARδ attenuates both small and largeintestinal adenoma growth, and PPARδ is required for the tumor-promotingeffects of PPARδ ligand (GW501516) and PGE2 in ApcMin/+mice." (PMID 18551185, 2008). "In summary, we show that PPARδ deficiency does not alter either lymphomagenesis or adenoma formation in mice with defective MMR." (PMID 16672050, 2006). "When Min mice were treated with azoxymethane,PPARδ levels were increased in flat dysplastic aberrant crypt foci, although the same authors indicatethat PPARδ expression in adenomas from Min mice does not differ compared to normal epithelium." (PMID 18528523, 2008).
cardiomyopathy (10 papers, 2010 to 2021). A disease of the heart muscle or myocardium proper. "Since disturbances in PPARα and PPARδ regulated FAO has been implicated in cardiomyopathy, we inferred that Med1 deletion in cardiomyocytes perturbs myocardial FAO and energy metabolism in csMed1-/- hearts." (PMID 27548259, 2016). "However, the activation of PPARδ by Ramipril failed to restore cardiac function in anthracycline-induced cardiomyopathy." (PMID 28672855, 2017).